CHRNA7 (cholinergic receptor nicotinic alpha 7 subunit)
Description:
Component of neuronal acetylcholine receptors (nAChRs) that function as pentameric, ligand-gated cation channels with high calcium permeability among other activities. nAChRs are excitatory neurotrasnmitter receptors formed by a collection of nAChR subunits known to mediate synaptic transmission in the nervous system and the neuromuscular junction. Each nAchR subunit confers differential attributes to channel properties, including activation, deactivation and desensitization kinetics, pH sensitivity, cation permeability, and binding to allosteric modulators. CHRNA7 forms homopentameric neuronal acetylcholine receptors abundantly expressed in the central nervous system, characterized by fast desensitization and high calcium permeability. Also forms heteropentamers with CHRNB2, mainly expressed in basal forebrain cholinergic neurons. Involved in the modulation of calcium-dependent signaling pathways and influences the release of neurotransmitters, including dopamine, glutamate and GABA. Also expressed in non-neuronal cells such as immune cells like lymphocytes, monocytes and macrophages. In T cells, activation induces metabotropic signaling that results in an increase of intracellular Ca2+ concentrations, independent of ionotropic receptor functions. In macrophages, required for acetylcholine-mediated inhibition of TNF and other inflammatory cytokine release. Once activated by acetylcholine, nicotine or other agonists, selectively inhibits production of pro-inflammatory cytokines while leaving anti-inflammatory cytokines undisturbed. Stimulates the cholinergic anti-inflammatory pathway, controlling inflammation by inhibiting NFKB nuclear translocation and activating the JAK2-STAT3 pathway, independently of ion channel activity. Also expressed in the urothelium where it modulates reflex bladder activity by increasing intracellular calcium through internal stores and decreasing basal ATP release (By similarity).
Synonyms: nAChR7; NACHRA7; a7nAChR; CHRNA7-2
Tractability: Small molecule: a drug acting on it is in phase 2 or 3 trials; a structure with a bound ligand is known; a high-quality ligand is known; it belongs to a druggable protein family. Antibody: UniProt places it where antibodies can reach, with high confidence; its Gene Ontology location is reachable by antibodies, with high confidence; UniProt predicts a signal peptide or a membrane-spanning region. PROTAC: a small molecule that binds it is known. Other modalities: a drug acting on it is in phase 2 or 3 trials.
Target class: Ion channel; Nicotinic acetylcholine receptor alpha subunit; Ligand-gated ion channel; Nicotinic acetylcholine receptor
Gene: Protein-coding gene on chromosome 15 (31,923,438 to 32,173,018, forward strand). Ensembl gene ENSG00000175344.
Subcellular location: Postsynaptic cell membrane; Cell membrane
Pathways (Reactome):
Neuronal System: Highly calcium permeable postsynaptic nicotinic acetylcholine receptors
Gene Ontology:
Molecular function: acetylcholine binding; acetylcholine receptor activity; acetylcholine-gated monoatomic cation-selective channel activity; amyloid-beta binding; chloride channel regulator activity; monoatomic ion channel activity; protein binding; protein homodimerization activity; toxic substance binding; transmembrane signaling receptor activity; calcium channel activity; neurotransmitter receptor activity; extracellular ligand-gated monoatomic ion channel activity
Biological process: acetylcholine receptor signaling pathway; calcium ion transport; chemical synaptic transmission; cognition; excitatory postsynaptic potential; intracellular calcium ion homeostasis; monoatomic ion transmembrane transport; negative regulation of amyloid-beta formation; negative regulation of canonical NF-kappaB signal transduction; negative regulation of cytokine production involved in inflammatory response; negative regulation of tumor necrosis factor production; positive regulation of angiogenesis; positive regulation of cell population proliferation; positive regulation of MAPK cascade; regulation of amyloid precursor protein catabolic process; response to acetylcholine; response to hypoxia; response to nicotine; signal transduction; synaptic transmission, cholinergic; activation of protein kinase C activity; dendrite arborization; dendritic spine organization; learning or memory; memory; and 20 more
Cellular component: acetylcholine-gated channel complex; plasma membrane; postsynaptic membrane; dendrite; endoplasmic reticulum membrane; membrane; neuron projection; plasma membrane raft; postsynapse; synapse; apical plasma membrane; axolemma; cholinergic synapse; external side of plasma membrane; postsynaptic specialization membrane; presynaptic membrane
Genetic constraint (gnomAD): Loss-of-function variants: 12 observed, 18.28 expected, observed/expected ratio (o/e) 0.66, 90% interval 0.42 to 1.06. The synonymous counts are far from expectation, so gnomAD's model fits this gene poorly and the ratio says little. Missense variants: 111 observed, 219.37 expected, observed/expected ratio (o/e) 0.51, 90% interval 0.43 to 0.59. Synonymous variants: 57 observed, 84.53 expected, observed/expected ratio (o/e) 0.67, 90% interval 0.54 to 0.84.
Gene-disease validity (ClinGen):
ClinGen rates the evidence that CHRNA7 causes each of these diseases.
epilepsy (inheritance undetermined): Refuted. A brain disorder characterized by episodes of abnormally increased neuronal discharge resulting in transient episodes of sensory or motor neurological dysfunction, or psychic dysfunction.
Homologues: Orthologues: chimpanzee CHRNA7 (100% identical), macaque CHRNA7 (99% identical), dog CHRNA7 (96% identical), mouse Chrna7 (93% identical), rat Chrna7 (93% identical), tropical clawed frog chrna7 (84% identical), zebrafish chrna7a (76% identical). Paralogues in human: CHRFAM7A (78% identical), CHRNA4 (39% identical), CHRNA2 (38% identical), CHRNA3 (37% identical), CHRNA10 (36% identical), CHRNB4 (34% identical), CHRNA9 (34% identical), CHRNA6 (34% identical), CHRNB2 (34% identical), CHRNA1 (33% identical), CHRNB3 (32% identical), CHRNA5 (31% identical), and 33 more.
Diseases named in the same sentence as CHRNA7 in open-access papers:
CHRNA7 is named in the same sentence as 116 diseases in open-access papers, as found by Europe PMC text mining. Sharing a sentence is not in itself a finding about the gene and the disease. The quoted sentences say what the papers report.
schizophrenia (42 papers, 2005 to 2025). A major psychotic disorder characterized by abnormalities in the perception or expression of reality. "Deletion of the 15q13.3 region containing OTUD7A and CHRNA7 is associated with schizophrenia with loss of function of OTUD7A resulting in impaired synapse function and development." (PMID 39387520, 2024). "Copy number variations (CNVs) of CHRNA7 gene have been identified in humans and are genetically linked to cognitive impairments associated with multiple disorders, including schizophrenia, bipolar disorder, epilepsy, Alzheimer’s disease, and others." (PMID 36684422, 2022). "CHRFAM7A, like CHRNA7, is polymorphic, and variants in this gene were associated with auditory pathology in cases of schizophrenia." (PMID 32640505, 2020). "The CHRFAM7A gene is a chimeric product of the CHRNA7 gene, which is genetically linked to multiple disorders with cognitive deficits, including schizophrenia and bipolar disorder." (PMID 33510659, 2020). "The α7 AChR-encoding gene, CHRNA7, is a susceptibility candidate gene in schizophrenia and the α7 AChR protein is currently seen as one of the most promising drug targets for schizophrenia." (PMID 30521579, 2018). "We also assessed some phenotypes related to human behavioral and psychiatric disease, such as hyperactivity, anxiety, depression, and schizophrenia-like phenotypes in Chrna7 deficient mice." (PMID 28045139, 2017). "We investigated five single nucleotide polymorphism (SNPs) of CHRNA7 and found that one SNP correlated well with the diagnosis of schizophrenia." (PMID 23717290, 2013). "Among the genes we identified, mutation of CHRNA7 has been observed in previous schizophrenia studies." (PMID 21390307, 2011). "The mapping of a putative Chrna7 neuronal enhancer inside the deletion has significant implications for understanding the transcriptional regulation of this schizophrenia-susceptibility candidate gene." (PMID 16280085, 2005). "Dysfunction associated with the gene encoding α7 nAChRs, CHRNA7, is linked to multiple psychiatric disorders that could be relevant to the current findings, including schizophrenia, bipolar disorder, ADHD, and Alzheimer’s disease." (PMID 37746145, 2023). "It has been reported that the nicotinic system may be deficient in patients with schizophrenia and studies found a deletion of 15q13.3 (chromosomal location of CHRNA7)." (PMID 36585402, 2022). "Additionally, single nucleotide polymorphisms in the promoter region of CHRNA7, encoding the a7nACh receptor subunit, significantly associated with schizophrenia." (PMID 32504122, 2020). "Further, genetic studies have implicated the CHRNA7 gene in schizophrenia and Alzheimer’s disease." (PMID 26086615, 2015). "The gene CHRNA7 involved in this CNV was found to be associated with schizophrenia and epilepsy." (PMID 24956385, 2014). "Identification of a neuronal enhancer and further studies in the human to examine for genetic variation and potential mutations might provide an explanation for a role of CHRNA7 as a schizophrenia-susceptibility gene." (PMID 16280085, 2005). "Interestingly, many individuals with schizophrenia show reduced nAChRs levels (such as α7), in particular in brain areas associated with cognitive processing, presumably owing to genetic anomalies (for example in CHRNA7)." (PMID 27483346, 2016). "They found that the endophenotypes associated with schizophrenia (i.e. inhibition of the P50 component of the cerebral evoked response to paired sounds) were diminished in subjects taking phosphatidylcholine even when they carry the genetic risk allele for schizophrenia (CHRNA7 risk allele)." (PMID 26120503, 2015). "Acetylcholine receptors are believed to be highly relevant to cognitive deficits in schizophrenia, although most research to date has been dedicated to a different acetylcholine receptor known as CHRNA7." (PMID 35316269, 2022). "The CHRNA7 antagonists have been reported to improve memory and executive function in schizophrenia patients." (PMID 34831111, 2021).
schizophrenia (continued). "The promoter methylation of CHRNA7 gene is thought to lead to a decreased expression of the gene seen in schizophrenia patients." (PMID 34831111, 2021). "CHRNA7 downstream gene of GNAL is also considered a promising drug target for the treatment of cognitive dysfunction in schizophrenia and improves memory and executive functions in patients and healthy individuals." (PMID 33087039, 2020). "RAD51AP1 and AQR are novel interactors of the calcium channel CACNA1C and the nicotinic receptor CHRNA7 respectively in the schizophrenia interactome, found to have an anti-correlated expression in schizophrenia and acetazolamide treatment." (PMID 31481665, 2019). "nAChR is an important neuron receptor in which one of the subunits alpha-7 (CHRNA7) has been recently studied as a new Schizophrenia drug target." (PMID 29184056, 2017). "Chrna7 mRNA levels were found to be decreased in post-mortem brains of schizophrenia patients which was likely due to increased expression of the transcription factor Activating Protein-2α (AP-2α), a negative regulator of AchE." (PMID 28069796, 2017). "Cholinergic receptor nicotinic alpha 7 (CHRNA7) gene encodes the alpha 7 nicotinic acetylcholine receptor (α7-nAChR) which is found on chromosome 15 q13.3, a region that has been identified as a schizophrenia candidate risk locus." (PMID 34831111, 2021). "In addition, a 2bp deletion in of the gene encoding for a human-specific chimeric protein, CHRFAM7A, containing a duplicate of exons 5-10 of CHRNA7, shows strong linkage to schizophrenia." (PMID 34684720, 2021). "A moderate risk of developing schizophrenia may be also associated with the presence of 2bp deletion in exon 6 of CHRFAM7A, a duplicated form of CHRNA7, generating a premature stop coding sequencing that produces a shortened peptide." (PMID 34066354, 2021). "In addition to the involvement of the CHRNA7 polymorphism in nAChR genes, in particular the D15S1360 associated with smoking by individuals with schizophrenia, there appears to be a significant association between the CHRNA4 rs3746372 allele 1 and smoking with a large number of cigarettes daily." (PMID 39370620, 2024). "Hence, disruption of the CHRNA7 by the 443 kb microduplication may contribute to the schizophrenia pathogenesis of our patient." (PMID 34659328, 2021). "In addition to the gene encoding the nAChR α7 subunit (CHRNA7) a partially duplicated variant (CHRFAM7A) has been identified in the human genome and both of these genes (CHRNA7 and CHRFAM7A) have been linked to schizophrenia." (PMID 25906356, 2015). "Copy number variations of CHRNA7 and RBFOX1 have been reported in patients with mental retardation, autism and schizophrenia or seizure." (PMID 22487416, 2012). "Shared genetic variation of CHRNA7 is, for example, reported in TUD and schizophrenia." (PMID 25060307, 2014).
epilepsy (21 papers, 2010 to 2025). "The first CNV identified was 15q13.3 microdeletion in CHRNA7 is linked with intellectual disability and epilepsy." (PMID 33096746, 2020). "Patients with CHRNA7 deletions have been identified as having high susceptibility for epilepsy." (PMID 36548204, 2022). "Those with 15q13.3 microdeletion syndrome, caused by heterozygous deletions involving the CHRNA7 gene, manifest variable neurological and behavioral symptoms, such as cognitive impairments, epilepsy, deficits in social interaction, decreased attention spans, and aggressive behaviors." (PMID 28045139, 2017). "Indeed, he carried a large deletion spanning the AS/PWS critical region (maternally inherited) and the CHRNA7 gene related to 15q13.3 deletion syndrome, associated with intellectual disability and epilepsy." (PMID 25435912, 2014). "Alterations involving the CHRNA7 gene, located in 15q13.3, have been reported as potential risk factors for ASD and epilepsy, although with variable penetrance and expressivity." (PMID 40943430, 2025). "Study in the subsequent year also found 15q13.3 microdeletion encompassing the CHRNA7 gene in patients with IGE, supporting role of 15q13.3 microdeletion as a prevalent genetic risk factor for epilepsy." (PMID 33096746, 2020). "Haploinsufficiency of CYFIP1 at 15q11.2, CHRNA7 at 15q13.3, NDE1 at 16p13.11 and PRRT2 at 16p11.2 has been implicated as risk-conferring mechanism for epilepsy and other neurodevelopmental phenotypes." (PMID 25950944, 2015). "CHRNA7 locates in 15q13.3, a region having recurrent deletion reported in epilepsy, late-onset Alzheimer's disease, mental retardation, seizures, and autism, among other pathologies." (PMID 21390307, 2011). "Five genes, ABCB1, ABCB4, CHRNA7, GABRA1, and GABRG2, are located within reported CNV regions and have been studied previously for their association with epilepsy as collected by HuGE." (PMID 21390307, 2011). "The gene within the 15q13.3 region that is most likely responsible for the epilepsy phenotype is CHRNA7, a subunit of the nicotinic acetylcholine receptor." (PMID 20502679, 2010). "After searching in DrugBank, we retrieved a total of 47 anti-epileptic drugs and 151 targets, of which identified 17 target genes (CACNA1A, CHRNA4,CHRNA7,GABRA1,GABRA2,GABRB2,GABRG2,GRIK1,GRIN1,GRIN2B,KCNQ2,KCNQ3,SCN1A,SCN2A, SCN3A,SCN8A and SCN9A) were overlapped with risk genes of epilepsy." (PMID 36006933, 2022). "Furthermore, the possible role of the CHRNA7 gene on autism and epilepsy has repeatedly emerged in the literature; however, its clinical significance is debated to this day." (PMID 31590400, 2019). "One should notice that genes such as CHRNA7 and GABRB3 are located within larger deletions containing other genes; so they might be questionable as bona fide epilepsy-associated genes." (PMID 30148849, 2018). "Both deletions and duplications of CHRNA7 have been associated with psychiatric symptoms like cognitive deficits, epilepsy, ASD, and SCZ, highlighting the importance of proper CHRNA7 expression for normal brain function." (PMID 40362210, 2025). "Incorporation of an expression dataset from Gene Expression Omnibus (GEO) further highlighted two genes, CHRNA7 and GABRA1, which are differently expressed between epilepsy patients and controls." (PMID 21390307, 2011). "Interestingly, two of the overlap genes, CHRNA7 and GABRA1, were also shown to be significantly differentially expressed between epilepsy patients and normal controls." (PMID 21390307, 2011).
cognitive deficits (15 papers, 2015 to 2025). "Another European study found −86 C/T promoter polymorphism in CHRNA7 gene was associated with slower progression from mild cognitive impairment to AD14." (PMID 27249957, 2016). "Notably, certain polymorphisms in the promoter region of the α7 nAChR gene (CHRNA7) are probable risk factors for neuropsychiatric diseases, such as major depression and schizophrenia and are associated with developmental disorders and cognitive impairments." (PMID 32245032, 2020). "CHRNA7 is related to several disorders that involve cognitive deficits, including neuropsychiatric, neurodegenerative, and inflammatory disorders." (PMID 35408823, 2022). "CHRNA7 is related to several disorders with cognitive deficits, including schizophrenia, P50 auditory gating deficits, autism, epilepsy, bipolar disorder, attention deficit hyperactivity disorder (ADHD), Down syndrome, Parkinson’s disease (PD), and Alzheimer’s disease (AD)." (PMID 35408823, 2022). "Additionally, it is thought that CHRNA7 deletions may contribute to the cognitive defects sometimes seen in 15q13.3 deletion syndrome." (PMID 36548204, 2022).
Alzheimer disease (12 papers, 2011 to 2025). A progressive, neurodegenerative disease characterized by loss of function and death of nerve cells in several areas of the brain leading to loss of cognitive function such as memory and language. "CHRNA7 encodes the α7 nicotinic acetylcholine receptor subunit, which is important to Alzheimer's disease (AD) pathogenesis and cholinergic neurotransmission." (PMID 24391883, 2013). "Furthermore, single nucleotide polymorphisms (SNPs) in the CHRNA7 gene (which encodes the α7 subunit) have been associated with dementia, Alzheimer's disease and schizophrenia." (PMID 38472514, 2024). "Interestingly, again, MAPK10 and CHRNA7—Alzheimer’s disease pathway-related genes—were recognized as the putative targets of specific brain-expressed lncRNAs." (PMID 40243843, 2025). "Remarkably, some of them are targeted by more than one miRNA, such as APBA2, which are involved in the “Alzheimer disease–amyloid secretase pathway” together with the CHRNA7 and MAPK10 genes, corroborating the importance of the regulation of their gene expression in AD." (PMID 40243843, 2025).